IFI44L (interferon induced protein 44 like)
Diseases named in the same sentence as IFI44L in open-access papers (continued):
Sharing a sentence is not in itself a finding about the gene and the disease.
cancer (19 papers, 2017 to 2024). A tumor composed of atypical neoplastic, often pleomorphic cells that invade other tissues. "Since CSCs are indicated to be associated with cancer recurrence, our previous experiments also indicated that IFI44L affects cancer stemness in HCC cells." (PMID 29848298, 2018). "Notably, the expression level of IFI44L has also been implicated in cancers." (PMID 34903206, 2021). "The ability of IFI44L to stimulate cellular apoptosis indicates its considerable promise as a therapeutic agent for cancer." (PMID 39737399, 2024). "Since IFI44L was implied to be correlated with cancer, we then investigated the impact of IFI44L on drug resistance." (PMID 29848298, 2018). "Also, its expression level increased significantly in EBV + samples compared to EBV- (FDR < 0.01) and TCGA data also showed that the expression level of IFI44L in cancer samples increased significantly compared to normal (FDR < 0.01)." (PMID 38355581, 2024). "It is evident that IFI44L exhibits varying expression patterns in different types of cancer." (PMID 39737399, 2024). "In general, IFI44L has a significant involvement in malignant tumors." (PMID 39737399, 2024). "Together, IFI44L may be involved in multiple cancer/immune-related pathways and play a pivotal role in TME." (PMID 35047409, 2021). "Functional enrichment analysis showed that IFI44L may participate in various cancer/immune-related pathways, including JAK/STAT signaling pathway and NF-κB signaling pathway." (PMID 35047409, 2021). "Besides PDPN, many of these molecules, such as IFI6, IFI27, IFI44L, and BOP1, also have been reported to be associated with carcinogenesis and treatment in other types of cancers." (PMID 31321241, 2019). "The functional role of IFI44L in different cancers still warrants further study." (PMID 29848298, 2018). "We then investigated if suppression of IFI44L by its small interfering RNAs (siRNA) could inhibit cancer stemness characteristics in HCC lines." (PMID 29848298, 2018). "To investigate whether IFI44L regulated cancer cell metastasis in vivo, we employed an experimental metastasis model via tail vein injection in SCID mice." (PMID 29848298, 2018). "Our data demonstrated that IFI44L is a potent negative regulator of Met/Src signaling pathway in modulating HCC cancer stemness and drug resistance and may serve as an important prognostic marker." (PMID 29848298, 2018). "We also found that MUC1-C is necessary for the expression of IFN-stimulated genes (ISGs), including IFIT1/3, OAS1/3, IFITM1, IFI44L and MX1, that promote DNA damage resistance, chronic inflammation and cancer progression." (PMID 34657147, 2022). "Amongst the upregulated genes were IFN stimulated genes (ISGs), including IFI44L and IFIT1, which were also induced in NK cells following reovirus treatment of cancer patients." (PMID 35156714, 2022). "Thus, the phenomenon that suppression of IFI44L promotes cancer stemness, migration, invasion, and pulmonary metastasis in HCC cells and overexpression of IFI44L results in restoring chemosensitivity observed in our study might be regulated via affecting Met/Src signaling pathway." (PMID 29848298, 2018). "IFI44L, one of the type I ISG, exhibits a low antiviral activity against HCV and is indicated to be correlated with some cancer recently although the reports are scarce." (PMID 29848298, 2018). "In summary, IFI44L may interact with the TME components and participate in various cancer and immune-related pathways and thus play a crucial role during NSCLC progression." (PMID 35047409, 2021). "In addition, there were multiple genes induced that are involved with cell and organelle structure and function (PNCK, UBD, CDH2, HERC5) and importantly, genes associated with the prostate, AR (MMP7, CDH2, ENO2, IGFBP3) and cancer (IFIT3, IFI44L)." (PMID 29416764, 2018). "To assess whether IFI44L level correlated with cancer stemness in HCC, we examined the protein expression level of IFI44L in HCC lines." (PMID 29848298, 2018).
cancer (continued). "Additionally, however, we noted a specific set of genes encoding chemokines and cytokines, namely CCL4, CCL8, CXCL10, CXCL11, IFI44L, IDO1, and IFNG that were upregulated in 9p CNG cancers." (PMID 29212506, 2017). "However these finding remains at the level of cell biology and none evident was reported that the deregulation of IFI44L may influence the progression or prognosis of cancer." (PMID 28881752, 2017).
bacterial infections (9 papers, 2017 to 2025). "Ifi44l promotes macrophage differentiation during bacterial infection and facilitates inflammatory cytokine secretion." (PMID 38696518, 2024). "We evaluated a RT-qPCR assay for a 2-transcript host expression signature (FAM89A and IFI44L genes) inferred from microarray data that allow to differentiate between viral and bacterial infection in febrile children." (PMID 31409879, 2019). "Here, we have shown that a RT-qPCR assay for a 2-transcript host expression signature (FAM89A and IFI44L genes) inferred from microarray data is able to efficiently separate viral from bacterial infections." (PMID 31409879, 2019). "Moreover, among the genes upregulated in pigs, genes involved in viral or bacterial infections, such as IFI44L, IL33, and RSAD2, were ranked at the top of the list." (PMID 38998110, 2024).
immune disorders (4 papers, 2014 to 2025). "Simultaneously, single-GSEA and immune infiltration analysis indicated immune dysfunction in both DCM and SLE, with both HERC6 and IFI44L significantly associated with immune cell infiltration." (PMID 40808946, 2025). "Additionally, the significant specificity of IFI44L expression in various types of tumors and immune diseases makes it a promising tool for distinguishing patients from healthy individuals." (PMID 39737399, 2024).
cardiovascular disease (1 paper, 2021). "Furthermore, three potential signature genes (IFIT2, IFIT3 and IFI44L) were identified in cardiovascular disease knowledge portal." (PMID 34884921, 2021).
endocrine diseases (1 paper, 2024). "Moreover, IFI44L has been linked to certain neurological, cardiovascular, chronic inflammatory, and endocrine diseases." (PMID 39737399, 2024).
heart disease (1 paper, 2021). "It is significant evidence that that three signature genes (IFIT2, IFIT3 and IFI44L) are linked to heart disease and used as potential biomarker for ISCM." (PMID 34884921, 2021).
neurological diseases (1 paper, 2013). "Remarkably, about 13% of the DEGs in FGF2 treated S252W fibroblasts were associated with neurological diseases (BAT3, HS6ST1, IFI44L, RFC3, RPS9, STRC and TCF19)." (PMID 23593218, 2013). "Seven (12.7%) of the DEGs were associated with neurological diseases (BAT3, HS6ST1, IFI44L, RFC3, RPS9, STRC and TCF19) according to the IPA analysis (p = 0.003)." (PMID 23593218, 2013).
vasculopathy (1 paper, 2024). "Considerable expression of IFI44L was observed in lung microvascular endothelial cells (MVECs) during the study of SSc-induced vascular lesions, this result may indicate the role of IFI44L in the vasculopathy caused by SSc." (PMID 39737399, 2024).
IFI44L also shares sentences with these, for which no sentence is quoted: hepatitis C (3 papers); periodontitis (2); tuberculosis (2); age-related macular degeneration (1); AIDS (1); bovine respiratory disease complex (1); brucellosis (1); Co-infection (1); cutaneous leishmaniasis (1); endothelial dysfunction (1); epilepsy (1); epileptic seizures (1); Epstein-Barr virus infection (1); Ewing sarcoma (1); fibromatosis (1); H1N1 virus infection (1); infectious disease (1); juvenile dermatomyositis (1); liver diseases (1); lung adenocarcinoma (1); myocardial infarction (1); oral cancer (1); ovarian carcinoma (1); pancreatic cancer (1); pneumonia (1); proliferative diabetic retinopathy (1); prostate carcinoma (1); psoriatic arthritis (1); pulmonary arterial hypertension (1); renal cell carcinoma (1).
A further 5 diseases each share a sentence with IFI44L in 1 paper.